BRCA1 (BRCA1 DNA repair associated)
Diseases named in the same sentence as BRCA1 in open-access papers (continued):
Sharing a sentence is not in itself a finding about the gene and the disease.
breast cancer (continued). "The majority of mutations in BRCA1 and BRCA2 (Breast Cancer Information Core, BIC database 2017) are frameshift changes resulting in nonfunctional proteins." (PMID 28944232, 2017). "While BRCA1‐related basal‐like breast cancer was previously postulated to originate from basal epithelial stem cells, cell‐of‐origin studies in GEMMs revealed that in fact, luminal progenitors are the source of basal‐like tumors." (PMID 28028012, 2017). "We depleted RAD52 in MDA-MB-436 BRCA1-/- breast cancer cells, stained nuclei with DAPI and measured nuclear abnormalities." (PMID 29145865, 2017). "We detected pathogenic mutations in nine of the 99 women in this group involving the ATM, BRCA1, CDH1, and CHEK2 genes, all of which have been associated with an increased risk of bilateral breast cancer in the previous studies." (PMID 28281021, 2017). "Some studies have shown that among the other outcomes of BRCA1/2 genetic cancer testing, breast cancer-related worry, anxiety and depression all increase in women testing positive, and decrease in those testing negative." (PMID 28570656, 2017). "About 10% of breast cancers are hereditary and can be attributed to germline mutations in breast cancer susceptibility genes, in particular BRCA1 and BRCA2 (BRCA1/2)." (PMID 28680148, 2017). "BRCA1 IHC staining was very weak in the stromal compartment in both normal breast and breast cancer tissues." (PMID 28863181, 2017). "Enhanced BRCA1 protein levels were also detected in additional breast cancer cell lines including a wild-type BRCA1 (i.e., MCF10A, HB2, and MDA-MB-231)." (PMID 28706506, 2017). "BRCA1 and BRCA2 are the first genes found to be associated with a higher predisposition to breast cancer." (PMID 28449691, 2017). "With regard to the effect on BRCA1 expression, we recently showed that IROSE ERα function in ERα/BRCA1-expressing breast cancer cells (e.g., MCF7)." (PMID 28052035, 2017). "We found similar results in the GSE19177 dataset which contains expression profiles for 19 BRCA1, 30 BRCA2 and 25 non-BRCA1/2 mutation familial breast cancer samples." (PMID 29146938, 2017). "In agreement with its tumor suppressor role, exogenous BRCA1 expression in breast cancer cells led to reductions in endogenous IGF1R protein and mRNA levels and a marked decrease in IGF1R promoter activity." (PMID 28706506, 2017). "This was subsequently verified in tumor samples from patients with BRCA1/2-mutant ovarian cancers, and also BRCA1/2-mutant breast cancers." (PMID 28829366, 2017). "In basal-like breast cancer cases, 63% had high BRCA1 expression while only 37% had a low BRCA1 expression (χ2 = 11.6, p b = 0.001)." (PMID 28863181, 2017). "VDR, RXR and PPARγ were detected in over 90% of triple negative BRCA1mut breast cancer and were significantly (VDR: p < 0.001, RXR: p = 0.010, PPARγ: p < 0.001) overexpressed in BRCA1 mutated as compared to sporadic cancer cases." (PMID 28427429, 2017). "Our data show that depletion of EEPD1 suppresses synthetic lethality, genome instability, mitotic catastrophe, and hypersensitivity to stress of replication of RAD52-depleted, BRCA1 mutant breast cancer cells." (PMID 29145865, 2017). "The breast cancer 1 early onset (Brca1), which is a tumor suppressor involved in cellular functions related to cell replication and DNA synthesis was found downregulated at 3 and 42 dpi." (PMID 28143561, 2017). "In striking contrast, DKO mice with homozygous deletion of Cobra1 and Brca1 (blue) exhibited significantly lower mammary tumour incidence than BKO and BKO, C-hemi mice." (PMID 28649985, 2017). "Survival assays confirmed the sensitivity of both Brca1‐ and Brca2‐deleted mouse mammary tumor‐derived cells lines to acetaldehyde." (PMID 28729482, 2017). "In initial experiments, we measured endogenous BRCA1 and IGF1R levels in a number of breast cancer cell lines expressing a wild-type or a mutant BRCA1 gene." (PMID 28706506, 2017).
breast cancer (continued). "In the group that received their results prior to surgery, median time from breast cancer diagnosis to BRCA1/2 positive results was 21 days." (PMID 28770017, 2017). "HOTAIR competes with BRCA1, a critical protein in breast cancer and is a critical regulator of genes involved in epithelial-to-mesenchymal transition." (PMID 29469819, 2017). "BRCA1 IHC staining was lower in breast cancer cases than normal breast tissue in both the cytoplasmic (cancer: 39.2±1.9; Normal: 58.5±3.9, p = 0.037) and nuclear fractions (cancer: 65.4±2.3; normal: 81.8±4.4, p = 0.007)." (PMID 28863181, 2017). "Module 2 includes genes whose abnormal function has been directly associated with breast cancer, such as MAPK14, BRCA1, CDH1, HIF1A, CDKN2A and other members/regulators of the CDK family." (PMID 29093438, 2017). "In the reported cross-sectional study of nurses and midwives, we examined several determinants of the methylation status in two suppressor genes, namely BRCA1 and BRCA2, whose silencing predisposes to breast cancer." (PMID 28594926, 2017). "We examined BRCA1 expression and subcellular localization in invasive breast cancer tissues from an ethnically diverse sample of 286 patients and 36 normal breast tissue controls." (PMID 28863181, 2017). "When providing genetic counseling to women with ovarian cancer and a recently identified BRCA1/BRCA2 mutation, genetic counselors have breast cancer risk management on their agenda." (PMID 28780755, 2017). "Improved assessments of risk have now been defined based on mutations in BRCA1 (Breast Cancer susceptibility gene 1: 39%–65% life-time risk), and BRCA2 (Breast Cancer susceptibility gene 2: 11%–37% life-time risk)." (PMID 28406427, 2017). "For example, women with pathogenic variants in breast cancer 1 (BRCA1) and BRCA2 were reported to have a cumulative lifetime risk of developing breast cancer between 41% and 90%." (PMID 29262565, 2017). "BRCA1 nuclear to cytoplasmic ratio was higher in breast cancer cells than in normal mammary epithelial cells." (PMID 28863181, 2017). "An analysis of three large, transcriptomic data sets from TCGA (The Cancer Genome Atlas) expression profile confirmed the inverse correlation between BRCA1 and β-hCG in human breast cancer." (PMID 28869585, 2017). "As an example, as recently as 5 years ago, a breast cancer patient who also has family history of young onset breast cancer would likely be tested in a healthcare setting for two genes (BRCA1 and BRCA2)." (PMID 29259772, 2017). "As expected, the majority of BRCA1 mutated patients had 3 or more cases of breast cancer in their families (73.9%), while most patients from BRCA1-VUS and BRCA1-WT groups (63.6% and 64.3%) reported up to two cases of breast cancer in the family (p = 0.007)." (PMID 27926510, 2017). "Mutations in BRCA1 and BRCA2 genes plays vital role in the majority of hereditary cases of breast cancer." (PMID 28235003, 2017). "As expected, BRCA1-/- breast cancer cells were sensitive to HU (control siRNA), and this was exacerbated by RAD52 depletion." (PMID 29145865, 2017). "The benefit of BRCA1 or BRCA2 genotyping in newly diagnosed breast cancer patients is increasingly evident." (PMID 28120249, 2017). "Further large-scale studies are required to assess the potential relevance of BRCA1 protein expression and localization in routine classification of breast cancer." (PMID 28863181, 2017).
breast cancer (continued). "Twenty years ago two genes, BRCA1 (MIM: 113705) and BRCA2 (MIM: 600185), which mutations confer a high risk to breast cancer were identified in families having four or more relatives with breast or ovarian cancer." (PMID 29088781, 2017). "Findings of this study indicate that alterations in BRCA1 protein expression and subcellular localization in breast cancer correlate with poor prognostic markers and aggressive tumor features." (PMID 28863181, 2017). "BRCA1 and BRCA2 germline mutations are more frequent in TNBC than in other types of breast cancer and affect ~30% of TNBC patients." (PMID 29138528, 2017). "To profile the functional impact and therapeutic relevance of BRCA1 variants, we developed a relatively simple drug sensitivity assay using the BRCA1-deficient, triple negative MDA-MB-436 breast cancer cells." (PMID 28398198, 2017). "There were 1134 women with breast cancer with verified HER2 and ER status who had undergone full mutation screening of BRCA1 and BRCA2." (PMID 27796713, 2017). "Song reported that the variant ratio of BRCA1 and BRCA2 in Shanghai was 11.4% and 2.9%, respectively, whereas in our study the variant ratio of BRCA1 and BRCA2 in breast cancer patients were 2.5% and 7.5%, respectively." (PMID 29093764, 2017). "Summary of nuclear, cytoplasmic and N/C ratio of BRCA1 expression among invasive breast cancer samples (IF staining)." (PMID 28863181, 2017). "Our data demonstrated that BRCA1 nuclear to cytoplasmic (N/C) ratios were significantly lower in breast cancer than normal breast tissues." (PMID 28863181, 2017). "Breast cancer 1 (BRCA1) and breast cancer 2 (BRCA2) are commonly used gene markers for breast cancer susceptibility." (PMID 28678153, 2017). "We validated our interaction results on brc-1, a worm ortholog of the human breast cancer gene BRCA1, and revealed new genes that regulate DNA damage response and interact with brc-1." (PMID 28506208, 2017). "Recently, PARP inhibitors were utilized to treat BRCA1 and BRCA2 mutation-associated ovarian and breast cancers." (PMID 28569838, 2017). "Specifically we show that depletion of EEPD1 rescues the synthetic lethality of RAD52-depleted, BRCA1 mutant breast cancer cells." (PMID 29145865, 2017). "We analysed primary mutation screens on women with breast cancer with unequivocal HER2 overexpression and assessed the likelihood of BRCA1/BRCA2 mutations by age, oestrogen receptor status and Manchester score." (PMID 27796713, 2017). "In male carriers of BRCA1/2 mutations, PRS that was based on 88 female breast cancer susceptibility variants was associated with breast cancer risk (odds ratio per standard deviation of PRS, 1.36; 95% CI, 1.19 to 1.56; P = 8.6 × 10−6)." (PMID 28448241, 2017). "In this case, we have shown that SERMs can regulate BRCA1 expression in breast cancer cells based on the ZNF423SNP genotypes." (PMID 28821270, 2017). "TNBC breast cancer cell lines with BRCA1 DNA methylation were more sensitive to PARP inhibitors when BRCA1 gene was methylated." (PMID 29138528, 2017). "Cell‐of‐origin studies can also deliver surprising results, as was the case for BRCA1‐related basal‐like breast cancer." (PMID 28028012, 2017). "Most pathogenic mutations were in genes with an established breast cancer risk (ATM, BRCA1, CHEK2, and PALB2)." (PMID 28281021, 2017). "There appeared to be considerable discrepancies in the causative variant rates of BRCA1 and BRCA2 in breast cancer patients in different areas of China." (PMID 29093764, 2017). "In spite of the big boost in breast cancer danger linked with BRCA1 and BRCA2 genes, they are responsible approximately 5% of all breast cancers, as merely 1 in 1000 females have acquired one of them." (PMID 28969709, 2017).
breast cancer (continued). "This study is, to the best of our knowledge, the largest population‐based study that comprehensively examined predictors of BRCA1/2 genetic testing among Black women with breast cancer." (PMID 28627138, 2017). "Analysis of 5848 putative deletions delineated by gene regions identified a total of 52 loci associated (at unadjusted P<0.05) with breast cancer risk, and 72 CNV loci associated with ovarian cancer risk for BRCA1 pathogenic variant carriers." (PMID 28145423, 2017). "We identified 43 deleterious mutations in BRCA1 and BRCA2 (39 new and 4 previously reported founder mutations), all of them involved in the development of breast cancer." (PMID 29021639, 2017). "We determined the spectrum of BRCA1 and BRCA2 deleterious mutations and variants in 467 breast cancer patients by full sequence analysis and large genomic rearrangement analysis." (PMID 28222693, 2017). "Germline mutations of BRCA1 and BRCA2 genes are involved in nearly 10% of ovarian cancers and 3–5% of breast cancers respectively." (PMID 28577564, 2017). "The role of BRCA1 in the transcriptional regulation of ER is a critical question in breast cancer research, with implications for both prevention and treatment." (PMID 28270739, 2017). "There is increasing evidence that BRCA1 germline mutant breast cancers present with above-average platinum sensitivity and increased sensitivity to poly-ADP ribose polymerase (PARP) inhibitors." (PMID 29138528, 2017). "Mutations in BRCA1 and BRCA2 genes increase the risk of ovarian cancer by 60% and breast cancer by up to 80% in women." (PMID 28651617, 2017). "In contrast, multiple breast primary cancers were only identified in BRCA2 pathogenic variant carriers in this cohort, suggesting a role for first-line BRCA1/BRCA2 testing in men with this presentation." (PMID 28008555, 2017). "TCGA analysis using cBioportal data sets confirms the inverse correlation between the levels of CGB5, CGB7 and BRCA1 in human breast cancer tissue samples." (PMID 28869585, 2017). "In this study, we analyzed the frequency of 7 BRCA1 and 25 BRCA2 variants from exonic and intronic regions identified previously in Malaysian breast cancer patients by germline analysis." (PMID 28222693, 2017). "FOXP3 targets and transcriptionally inhibits the breast cancer suppressor gene, BRCA1, which reduces the radioresistance of breast cancer cells." (PMID 28562349, 2017). "We used the estimated OR for the breast cancer overall PRS and the prostate cancer PRS from the combined analysis of BRCA1/2 samples to calculate male breast and prostate cancer risks at the 5th, 10th, 50th, 90th, and 95th percentiles of PRS distributions." (PMID 28448241, 2017). "There was evidence for a PRSxage interaction for the ER-negative breast cancer PRS for BRCA1 carriers (P = 3×10−6) and for the overall breast cancer PRS for BRCA2 carriers (P = .01)." (PMID 28376175, 2017). "In theory, another possibility is that consanguinity protects against breast cancer by decreasing the number of BRCA1 and BRCA2 cancer cases as homozygotes of these genes are early aborted." (PMID 29157216, 2017). "In keeping with the focus of the present work, we confirmed that MUC1 expression negatively correlates with that of BRCA1 in datasets from breast cancers and NSCLCs." (PMID 28785086, 2017). "In agreement with ER+ breast cancer cell line data, BRCA1 protein was significantly decreased after overexpressing CTSO in triple negative breast cancer cells." (PMID 28968398, 2017). "If the population-based ER-negative PRSs were also associated primarily with ER-negative breast cancers in BRCA1 mutation carriers, the ER-negative PRS would be more predictive of breast cancer in BRCA1 carriers at younger ages." (PMID 28376175, 2017). "BRCA1 and BRCA2, the first gene mutations associated with a predisposition for a high risk of breast cancer, confer an estimated risk of 65 and 45% for BC and 39 and 10% for OC, respectively." (PMID 27779110, 2017).
breast cancer (continued). "Women who have a positive family history of breast carcinoma are 2–4 times more likely to develop the cancer, especially the females who are the carriers of BRCA1 or BRCA2 genes have the significant chance to develop carcinoma of breast." (PMID 28969709, 2017). "The diagnostic value of BRCA promoter methylation analysis in distinguishing BRCA1/2-related from sporadic breast carcinomas seems to be considerably dependent on the targeted CpG sites." (PMID 28569220, 2017). "This miRNA directly targeted 3’-untranslated regions of BRCA1, (Breast Cancer gene) and the suppression of BRCA1 expression improved docetaxel-resistance in BC cells." (PMID 28574440, 2017). "In other words, we sought to determine to what extent BRCA1/2 promoter methylation can be detected in BRCA1/2-related compared with sporadic breast carcinomas." (PMID 28569220, 2017). "The diagnostic value of BRCA promoter methylation analysis in distinguishing BRCA1/2-related and sporadic breast carcinomas is considerably dependent on the targeted CpG sites." (PMID 28569220, 2017). "Breast cancer, with extensive hypermethylation in the BRCA1 promoter, correlates with a reduced BRCA1 expression." (PMID 27413552, 2016). "Impact of BRCA1/2 P/LP variants and other variables on the DFS and OS of breast cancer patients (Stage 0~III)." (PMID 27257965, 2016). "We identified 21.5% of patients harboring BRCA1/BRCA2 mutations and characterized the genetic ancestry of a sample group at-risk for hereditary breast cancer showing once again how admixed is the Brazilian population." (PMID 27741520, 2016). "BRCA1 promoter methylation has a statistical significance on survival in breast cancer patients (HazR = 1.465, P = 0.000)." (PMID 27027444, 2016). "We examined BRCA1 promoter methylation levels in 154 breast cancer tissues and their adjacent normal breast tissues." (PMID 27027444, 2016). "In CMT, BRCA1, and BRCA2 have, for example, already been investigated and were associated with an increased mammary tumor risk in English Springer Spaniels." (PMID 27187374, 2016). "In some breast cancer patients, loss of RAD17, RAD50, and RAP80 s genes which participate into the BRCA1‐dependent DNA repair was associated with significantly increased genomic instability and poor patient survival." (PMID 26663100, 2016). "The average ages at breast cancer diagnosis among the groups were 41.4 (BRCA1+), 43.6 (BRCA2+), and 47.7 (BRCAx)." (PMID 27148484, 2016). "We will also look into the mechanisms of BRCA1 promoter methylation specifically in breast cancer patients." (PMID 27027444, 2016). "Consistently, heterozygous germline deletion of Brca1 or specific deletion of Brca1 in mouse mammary epithelial cells rarely develop mammary tumors." (PMID 27811360, 2016). "We noticed that both the tumor cell morphology and expression pattern of CK5 and CK14 in p16;Brca1 double mutant mouse mammary tumors resembled human basal-like breast cancers that were ER-negative and expressed low BRCA1." (PMID 27811360, 2016). "The purpose of this pilot study is to investigate the contribution of common BRCA1 and BRCA2 mutations to early onset and familial cases of breast cancer in Uzbekistan." (PMID 29138730, 2016). "PALB2 has recently been reported to confer a breast cancer risk comparable to that of BRCA2 mutations, indicating the need to include it in the clinical diagnostics along with BRCA1 and BRCA2 mutation testing." (PMID 26820313, 2016).